ADAMTS1 (ADAM metallopeptidase with thrombospondin type 1 motif 1)
Diseases named in the same sentence as ADAMTS1 in open-access papers (continued):
Sharing a sentence is not in itself a finding about the gene and the disease.
age-related macular degeneration (1 paper, 2023). Age-related loss of vision in the central portion of the retina (macula), secondary to retinal degeneration. "ADAMTS genes (ADAMTS1, ADAMTS6 and ADAMTS9) may associate with age-related macular degeneration and MAP1B was higher expression in the macula of human eye." (PMID 37389979, 2023).
AIDS (1 paper, 2016). A syndrome resulting from the acquired deficiency of cellular immunity caused by the human immunodeficiency virus (HIV). "Among downstream genes, two specific metalloproteases, ADAMTS1 and 9, are strongly expressed in AIDS-KS tissues and contribute to KSHV-infected endothelial cell invasiveness through up-regulation of IL-6 and VEGF." (PMID 26675551, 2016).
ameloblastoma (1 paper, 2022). The most common odontogenic tumor, arising from the epithelial component of the embryonic tooth and usually affecting the molar-ramus region of the mandible or maxilla. "In the present study, all samples of ameloblastoma expressed the ADAMTS-1 mRNA by RT-PCR and immunohistochemical analysis showed high expression in protein." (PMID 36338393, 2022). "This study showed a distinct expression of ADAMTS-1 and versican in ameloblastoma and DF, with ADAMTS-1 protein higher expression observed in ameloblastoma and possibly cleaved versican." (PMID 36338393, 2022). "The immunostaining of ADAMTS-1 in ameloblastoma was most prominent in the parenchyma than the stroma." (PMID 36338393, 2022). "The present study demonstrated an expression of ADAMTS-1 mRNA in ameloblastoma, DF by RT-PCR, and immunostaining, which showed ADAMTS-1 protein was highly expressed in ameloblastoma than in DF." (PMID 36338393, 2022). "Although ADAMTS-1 has been expressed more in DF than in ameloblastoma by RT-PCR, the immunochemistry analysis showed high ADAMTS-1 expression in ameloblastoma." (PMID 36338393, 2022). "Indirect immunofluorescence detected the ADAMTS-1 and versican expression in cell lines derived from ameloblastoma." (PMID 36338393, 2022). "In our 20 samples of ameloblastoma, ADAMTS-1 had been amplified in all samples of ameloblastoma and 10 DF samples." (PMID 36338393, 2022). "Thus, this study aimed to investigate the gene and protein expression of ADAMTS-1 and versican in ameloblastoma." (PMID 36338393, 2022). "Possible hypoxia conditions are involved in the expression of ADAMTS-1 in ameloblastoma." (PMID 36338393, 2022). "As in this study, ameloblastoma also expressed MMP-1 and ADAMTS-1, which were highly expressed in our study, suggesting that ADAMTS-1 and MMP-1 could have the same mechanism and may be associated with the behavior of ameloblastoma." (PMID 36338393, 2022). "ADAMTS-1 and versican were overexpressed in DF than ameloblastoma by RT-PCR." (PMID 36338393, 2022). "However, in the immunolocalization analysis, ADAMTS-1 was expressed in ameloblastoma more than in DF and versican immunostaining obtained a similar pattern between ameloblastoma and DF." (PMID 36338393, 2022). "In this pilot study, we hypothesized that ameloblastoma may express ADAMTS-1, which can contribute to locally invasive tumor, through the degradation of versican." (PMID 36338393, 2022). "Our goal was to elucidate whether ADAMTS-1, a member of the metalloproteinase family, and versican are expressed in ameloblastoma and whether they are correlated with biological behavior in the tumor." (PMID 36338393, 2022). "Based on this finding and the high expression of ADAMTS-1, protein in the ameloblastoma in the present study may suggest that this enzyme may participate in the tumor invasion mechanism of this neoplasia, especially for the degradation of the substrate (versican) in the ECM." (PMID 36338393, 2022).
amyloid (1 paper, 2022). "In addition, we also verified that the hippocampal amyloid load of AD mouse model was alleviated by the introduction of ADAMTS1, and thus spatial cognition was restored as well." (PMID 36016856, 2022). "Our findings identified ADAMTS1 as a novel APP hydrolase that connected the genetics and cognitive activities with hippocampal amyloid processing." (PMID 36016856, 2022).
anovulation (1 paper, 2020). The absence of ovulation. "Whether low ADAMTS1 expression is the cause of anovulation in PCOS patients needs to be investigated further." (PMID 31974739, 2020).
arteriosclerosis (1 paper, 2019). A vascular disorder characterized by thickening and hardening of the walls of the arteries. "ADAMTS1 (a disintegrin and metalloproteinase with thrombospondin motifs 1) is a member of the MMP family involved in several physiological and pathophysiological processes like cellular differentiation, angiogenesis, inflammation, cancer development and arteriosclerosis." (PMID 31036020, 2019).
breast adenocarcinoma (1 paper, 2013). "MCF7 cells were used in migration experiments to address whether ADAMTS-1 knockdown stimulated migration in other cell lines, including this non-invasive breast adenocarcinoma cell line." (PMID 23289900, 2013).
Brugada syndrome (1 paper, 2023). A genetically heterogeneous condition characterized by complete or incomplete right bundle branch block accompanied by ST elevation in leads V1-V3. "At least seven genes putatively mapped by our significant non-reference TEs have been already associated with schizophrenia: LRRC4C, LRRC7, ST8SIA4, MGAM, ADAMTS1, MIR548AJ2 and SCN5A, which is also linked to the Brugada syndrome." (PMID 37244930, 2023).
chronic kidney disease (1 paper, 2014). Impairment of the renal function secondary to chronic kidney damage persisting for three or more months. "Using a murine model of AVF with chronic kidney disease, we reduced ADAMTS-1 mRNA expression with a small hairpin RNA that inhibits ADAMTS-1 expression (LV-shRNA-ADAMTS-1) at the time of fistula creation." (PMID 24732590, 2014).
colitis (1 paper, 2020). Inflammation of the colon. "Stainings for Adamts1, Adamts5, and Bmp1 showed similar distribution patterns as the MPO-staining, indicating that these proteases are contributed not by the colon epithelium, but by invading neutrophils/monocytes on colitis induction." (PMID 32160911, 2020).
cyst (1 paper, 2021). A sac-like closed membranous structure that may be empty or contain fluid or amorphous material. "Therefore, our objective was to verify the expression of ADAMTS-1, versican and pEGFR in Periapical Granuloma (PG) and in the Radicular Cyst (RC) since they are the most common lesions of the periapex." (PMID 33676487, 2021).
diarrheal disease (1 paper, 2022). The condition of having at least three loose or liquid bowel movements each day. "Our study reports five such proteins, RAPH1, GCNT7, ADAMTS1, GLI1, and SEC31B, which are strong binding partners of other significant proteins and could thus be targeted for the discovery of a common medication system against diarrheal disease." (PMID 36473896, 2022).
endometrial cancer (1 paper, 2010). Primary or metastatic malignant neoplasm involving the endometrium (mucous membrane that lines the endometrial cavity). "Signal transduction pathways regulating ADAMTS1 expression in Ishikawa cells stably expressing the FP receptor to levels seen in endometrial cancer (FPS cells) were determined by quantitative RT-PCR analysis." (PMID 20840749, 2010). "We localised the site of expression of ADAMTS1 to the neoplastic epithelial and vascular cells of endometrial cancer tissues by immunohistochemistry and confocal laser microscopy." (PMID 20840749, 2010). "We found that ADAMTS1 expression was elevated in the glandular and vascular compartments in endometrial cancer compared with normal endometrium." (PMID 20840749, 2010).
esophageal cancer (1 paper, 2024). A primary or metastatic malignant neoplasm involving the esophagus. "In esophageal cancer cells, loss of TGF-β was shown to activate ADAMTS1-mediated EGF-dependent invasion." (PMID 39333870, 2024).
esophageal SCC (1 paper, 2024). "As to the role of ADAMTS1 in tumor types located on the head and neck, ADAMTS1 was shown to sequester vascular endothelial growth factor C (VEGF-C) and block the lymphangiogenesis and lymphatic metastasis of esophageal SCC." (PMID 38263290, 2024).
fatty liver (1 paper, 2023). "The two metallopeptidases ADAMTS1 and ADAMTS4 were related to ATH in practically all of the databases we consulted, while their relationship with the liver was shared between oncologic processes and fatty liver." (PMID 36835545, 2023).
hyperemesis gravidarum (1 paper, 2022). Severe, intractable vomiting during pregnancy (usually the first trimester) accompanied by dehydration, weight loss, and electrolyte imbalances. "We aimed to investigate the levels of ADAMTS-1, which is secreted from the extracellular matrix during trophoblastic invasion in hyperemesis gravidarum (HEG)." (PMID 35725415, 2022).
Hyperglycemia (1 paper, 2015). An increased concentration of glucose in the blood. "The detection of up-regulated ADAMTS1 expression in high-glucose cultured HNSCC cells could therefore be one of the molecular promoters for hyperglycemia-mediated cell motility." (PMID 26337468, 2015).
hyperopia (1 paper, 2011). A refractive error in which rays of light entering the eye parallel to the optic axis are brought to a focus behind the retina, as a result of the eyeball being too short from front to back. "The modulation of ADAMTS1 appeared as an early, transient response to both hyperopia and myopia." (PMID 21541268, 2011).
influenza (1 paper, 2017). An acute viral infection of the respiratory tract, occurring in isolated cases, in epidemics, or in pandemics; it is caused by serologically different strains of viruses (influenzaviruses) designated A, B, and C, has a 3-day incubation period, and usually lasts for 3 to 10 days. "The transgene contains full-length Adamts1 complementary DNA (cDNA) with a human influenza hemagglutinin-tag sequence subcloned behind aP2 promoter and enhancer elements." (PMID 28939843, 2017).
invasive carcinoma (1 paper, 2024). A carcinoma that is not confined to the epithelium, and has spread to the surrounding stroma. "A negative correlation was also observed between ADAMTS-1 expression in in situ stroma and VKINE expression in situ (r = −0.4; p = 0.03) and invasive carcinoma cells (r = −0.3; p = 0.01)." (PMID 39682243, 2024).
ischemic cardiomyopathies (1 paper, 2023). "Of these, ADAMTS1 was noted to cause plaque instability, predisposing the individuals to ischemic cardiomyopathies and infarctions." (PMID 37623681, 2023).
ischemic heart disease (1 paper, 2021). "However, lots of DEGs were not previously reported in the investigation of VNS, such as CD163, CD48, DDit4, and ADAMTS1, which have been demonstrated close association with ischemic heart disease." (PMID 33981734, 2021).
leukemia (1 paper, 2010). A malignant (clonal) hematologic disorder, involving hematopoietic stem cells and characterized by the presence of primitive or atypical myeloid or lymphoid cells in the bone marrow and the blood. "The application on a dataset of leukemia patients identifies eQTLs in the regions of the GART, PCP4, DSCAM, and RIPK4 genes that regulate ADAMTS1, a known leukemia correlate." (PMID 21044360, 2010).
liver cancer (1 paper, 2025). An epithelial or non-epithelial malignant neoplasm that arises from the liver. "Elevated ADAMTS1 expression is associated with improved survival outcomes in male liver cancer patients." (PMID 40867252, 2025). "Thus, higher expression of GPER and ADAMTS1, especially in men with liver cancer, was associated with better OS." (PMID 40867252, 2025). "Additionally, the clinical relevance of GPER and ADAMTS1 is highlighted by their association with higher expression levels and improved OS in men with liver cancer." (PMID 40867252, 2025). "The aim of this study was to investigate the relationship between G protein-coupled estrogen (GPER) activation via its agonist, G1, and ADAMTS1 in suppressing liver cancer metastasis." (PMID 40867252, 2025). "Overall, these findings suggest that GPER activation through G1 influences ADAMTS1 expression, potentially regulating the growth and metastasis of liver cancer." (PMID 40867252, 2025). "Our findings suggest that regulating ADAMTS1 via GPER activation is a potential therapeutic target in liver cancer, particularly inhibiting metastasis and improving patient outcomes." (PMID 40867252, 2025). "ADAMTS1 is associated with hepatic fibrosis suppression; however, the role of ADAMTS1 in liver cancer metastasis remains unclear." (PMID 40867252, 2025). "In this study, we aimed to investigate the relationship between GPER activation via G1 and ADAMTS1 in suppressing liver cancer metastasis, proposing a mechanism wherein GPER activation may suppress metastasis through ADAMTS1 regulation." (PMID 40867252, 2025).
male infertility (1 paper, 2022). The inability of the male to effect fertilization of an ovum after a specified period of unprotected intercourse. "Recently, insufficient ADAMTS1 expression was also reported to result in male infertility." (PMID 35471239, 2022).
multiple myeloma (1 paper, 2024). "In contrast, in the context of multiple myeloma, ADAMTS-1 was overexpressed and identified as one of the main versicanases." (PMID 39682243, 2024).
Nephroblastoma (1 paper, 2006). An embryonal neoplasm characterized by the presence of epithelial, mesenchymal, and blastema components. "Northern blotting of RNA species isolated from normal kidneys and four different MAV-induced nephroblastomas indeed established that ADAMTS1 was overexpressed in the 4 MAV-induced nephroblastomas as compared to normal tissue." (PMID 16403231, 2006).
pancreatic adenocarcinoma (1 paper, 2019). "Methylation of ADAMTS1 was detected in 87.2% (34/39) pancreatic adenocarcinomas." (PMID 30953539, 2019).
periodontitis (1 paper, 2022). An acute or chronic inflammatory process that affects the tissues that surround and support the teeth. "Besides, ADAMTS-1 was found to be significantly increased in the oral environment in chronic and aggressive periodontitis patients." (PMID 36338393, 2022).
Pleural effusion (1 paper, 2013). The presence of an excessive amount of fluid in the pleural cavity. "In addition we detected a homozygous deletion at 21q that simultaneously deleted the metallopeptidases ADAMTS1 and ADAMTS5 that was present only in the pleural effusion populations." (PMID 23372550, 2013).
preeclampsia (1 paper, 2022). Preeclampsia is a hypertensive disorder of pregnancy that is characterized by new-onset hypertension with proteinuria presenting after 20 weeks of gestation, and depending on mild or severe forms may initially present with severe headache, visual disturbances, and hyperreflexia. "In the literature, there is no study investigating the relationship between ADAMTS-1 levels and HEG, but there was a study investigating its levels in preeclampsia patients." (PMID 35725415, 2022).
premature ovarian failure (1 paper, 2022). "ADAMTS1 was reported relevant to premature ovarian failure and menopause and to be significantly increased in granulosa cells in PCOS." (PMID 36286390, 2022).
progeria (1 paper, 2022). "ADAMTS15, along with ADAMTS1, 4, 5, 9, and 20, is involved in several processes, including palate formation, skin pigmentation, myogenesis, and cardiac development, all of which appear to be affected by progeria." (PMID 36289702, 2022).
proliferative diabetic retinopathy (1 paper, 2022). Advanced retinopathy due to diabetes mellitus characterized by the formation of new vessels in the retina. "We analyzed the expression of ADAMTS proteinases ADAMTS-1, -2, -4, -5 and -13; their activating enzyme MMP-15; and the degradation products of proteoglycan substrates versican and biglycan in an ocular microenvironment of proliferative diabetic retinopathy (PDR) patients." (PMID 36144730, 2022).
retinal ischemia (1 paper, 2022). A ischemic disease that involves the retina. "Similarly, a previous study demonstrated increased ADAMTS-1 expression, along with VEGF expression, in the retina of a mouse model of oxygen-induced retinal ischemia and neovascularization." (PMID 36144730, 2022).
salpingitis (1 paper, 2012). Acute or chronic inflammation of the fallopian tube. "Briefly, ADAMTS1 (disintegrin and metalloproteinase with thrombospondin motif 1) has been associated with inflammatory processes, and its activity could be related to salpingitis triggered by sexually transmitted pathogens." (PMID 22897899, 2012).
sarcoidosis (1 paper, 2020). Sarcoidosis is a multisystemic disorder of unknown cause characterized by the formation of immune granulomas in involved organs. "We have identified new genomic markers for sarcoidosis, ADAMTS1, CXCL2, and NPR1." (PMID 33276795, 2020).
schizophrenia (1 paper, 2023). A major psychotic disorder characterized by abnormalities in the perception or expression of reality. "It is further interesting that at least three of these genes (ADAMTS1, LRRC4C, and LRRC7) have already been associated with schizophrenia." (PMID 37244930, 2023).
Splenomegaly (1 paper, 2018). Abnormal increased size of the spleen. "We found that Adamts1 deficiency led to a pro-inflammatory setting in the spleen, mostly showing a relevant increase in the number of CD3+ cells, correlating with the obvious splenomegaly of these animals." (PMID 30166561, 2018).
squamous cell carcinoma (1 paper, 2006). A carcinoma arising from squamous epithelial cells. "On the opposite, we report a decreased expression of ADAMTS-1 mRNA in squamous cell carcinomas and adenocarcinomas when compared to corresponding control samples." (PMID 16495931, 2006).
steatosis (1 paper, 2021). Increased lipid within the cytoplasm of cells. "Eventually, we determined 10 hub genes (Down-regulated genes: MYC, TGFB3, ADAMTS1, THBS1, RASD1, PCDH20; Up-regulated genes: MAMDC4, CYP7A1, GINS2, and PDLIM3) related to NAS and steatosis." (PMID 34777484, 2021).
tendinopathy (1 paper, 2023). "For PERI cells, vitamin C reduced expression of ADAMTS1, which is a protease that has been shown to be active in degradative processes of tendinopathy." (PMID 38069418, 2023).
testicular germ cell tumor (1 paper, 2025). A germ cell tumor arising from the testis. "In this study, we demonstrated that ADAMTS1 is C‐mannosylated at Trp562 and Trp565 in human testicular germ cell tumor NEC8 cells." (PMID 40878842, 2025).
triple-negative breast carcinoma (1 paper, 2013). An invasive breast carcinoma which is negative for expression of estrogen receptor (ER), progesterone receptor (PR), and human epidermal growth factor receptor 2 (HER2). "Our study was the first to describe lower levels of ADAMTS-1 protein in triple-negative breast cancer cases (ER-, PR-, and Her-2), and our immunoblot analyses indicated that ADAMTS-1 expression was reduced in tumors in comparison to contralateral normal tissues." (PMID 23289900, 2013).
ulcerative colitis (1 paper, 2023). An inflammatory bowel disease involving the mucosal surface of the large intestine and rectum. "However, ADAMTS-1, -4, -5, and IL-17 A protein expressions in certain regions of inflamed tissues of ulcerative colitis patients revealed to be significantly increased stained areas, especially in the lamina propria." (PMID 37798683, 2023). "Immunohistochemical analysis of ADAMTS-1, ADAMTS-4, ADAMTS-5, and IL-17 A protein in the colon tissues of healthy human control and those with ulcerative colitis." (PMID 37798683, 2023).